IGFBP2 (insulin like growth factor binding protein 2)
Diseases named in the same sentence as IGFBP2 in open-access papers (continued):
Sharing a sentence is not in itself a finding about the gene and the disease.
tumor (continued). "We performed Western blotting analysis on molecules whose expressions were changed in relatively a large number of tumor tissues, including cyclin B1, caveolin 1, collagen VI, ACC1/pS79, CHK2, and IGFBP2." (PMID 22348039, 2012). "The Tests of Normalityb of IGFBP-2 and IGF-2R in 25 pairs of tumor (T) and paratumorous (P) tissues." (PMID 23071652, 2012). "Some proteins from this list have also been identified in tumor studies as clinical outcome predictors (NOV, CLU TNC, POSTN, IGFBP2, LCN2) or mediators of resistance to chemotherapy (CLU, FBLN1, THBS, STIP1, PTGES3, IGFBP4, ATOX1)." (PMID 19936259, 2009). "Importantly, combinatorial blockade of IGFBP2 and CD47 synergistically suppressed tumor growth and prolonged survival in orthotopic GBM models." (PMID 41620401, 2026). "Here, we integrated single cell RNA sequencing and proteomic analysis to identify that insulin-like growth factor binding protein 2 (IGFBP2) was co-expressed with CD47 in hypoxic mesenchymal-like GBM subpopulations, synergistically promoting tumor progression and immune evasion." (PMID 41620401, 2026). "Specifically, proteomic analyses have revealed several CAAT-derived factors, such as leptin and insulin-like growth factor binding protein 2 (IGFBP2), which activate pro-oncogenic pathways, including the PI3K/AKT and STAT3, thereby promoting tumour growth and resistance to therapy." (PMID 41388212, 2025). "Notably, OSMR, IGFBP2, and LOXL1 are highly expressed in multiple signaling pathways involved in tumor‐related biological processes such as apoptosis, inflammatory responses, EMT, and adherens junctions." (PMID 41498024, 2025). "Compared to the FMT-PCa group, the FMT-PCa-ICA + CUR group experienced a reduction in the expression of IGFBP2 in the tumor tissues, with no significant change in DNMT1." (PMID 38778379, 2024). "Additionally, upon the addition of anti-IGFBP2 treatment to ICA + CUR + SCFAs + IgG, the tumor shrunk, Ki67 levels in the tumors decreased, and the tumor-promoting effect of SCFAs on tumor growth was weakened." (PMID 38778379, 2024). "Compared to the ICA + CUR group, the ICA + CUR + SCFAs group showed a significant increase expression of IGFBP2 in the liver and tumor tissues, while DNMT1 expression showed no significant change." (PMID 38778379, 2024). "Our previous study has shown that IGFBP2 is expressed in microvesicles released from NSCLC cells and is highly expressed in the marginal region of NSCLC tumors, indicating its potential role in remodeling the tumor microenvironment." (PMID 38918360, 2024). "Again, this is consistent with previous reports of an IGFBP-2 correlation with an increased malignant status of the tumor but not IGFBP-3." (PMID 38137390, 2023). "Additionally, immunofluorescence assay demonstrated an enhanced co-localization of IGFBP2 and LRP6 in the mouse tumor tissues." (PMID 37957694, 2023). "However, there was a clear reduction in cancer cell invasion into the surrounding stroma in the IGFBP2 TIF co-xenografts, supporting the idea that IGFBP2 plays a protective role in the stroma and, when present, is able to contain the tumor." (PMID 37436978, 2023). "Moreover, adipocytes in the IDC samples had significantly reduced IGFBP2 expression, compared to the DCIS and healthy samples, and this was further reduced in adipocytes contained within the tumor borders, compared to those at the invasive front." (PMID 37436978, 2023). "Besides, we found that expression of IGFBP2 negatively correlated with OS in PCPG patients, which was consistent with previous studies which also identified IGFBP2 as an oncogene in various tumor types." (PMID 36497433, 2022). "Among the other hepatokines investigated in our study, high levels of AHSG, IGFBP1 and IGFBP-2 are found in the serum and HCC tissues of patients, whereas LECT2 expression is usually decreased and appears to behave as a tumour suppressor under the control of beta-catenin in the liver." (PMID 35409319, 2022).
tumor (continued). "Collectively, our data suggest circSMARCA5 as an upstream regulator of the expression of TS miRNAs 126-3p and 515-5p and their downstream targets IGFBP2 and NRAS mRNA in GBM cells, extending our knowledge on the disrupted tumor suppressive pathways mediated by circSMARCA5 in GBM cells." (PMID 36430152, 2022). "Conflicting points of view do not fully explain the oncogenic or tumor suppressive effect of IGFBP2, stating that more in vitro functional studies are needed." (PMID 36142846, 2022). "Although some studies indicated the tissue expression of IGFBP‐2 but not IGFBP‐3 has a tumor suppressor effect and it is a chemosensitivity marker in UC." (PMID 35368130, 2022). "Therefore, we conclude that m6a-related mRNAs, especially METTL14, IGFBP2, and FTO, can influence the clinical outcome of HCC by altering tumor cell proliferation and survival." (PMID 35734590, 2022). "Identification of the role of IGFBP2 with respect to immunoregulation in PDAC may open new immunotherapeutic avenues, including transforming PDAC from an immuno-cold tumor into a hot tumor." (PMID 36556226, 2022). "Moreover, tumor-promoting genes such as HMGB3 and IGFBP2 were highly expressed in P01-C2, which implied a poorly differentiated subpopulation of malignant cancer cells." (PMID 35874770, 2022). "PLEKHS1 expression was significantly increased in G3T1 compared to G1Ta tumours (p = <0.01), whilst IGFBP2, IGFBP4, and IGF1R were significantly reduced in the more advanced tumour group (p = <0.010.03, <0.01, respectively), which were similar results to those observed in CIS." (PMID 34681810, 2021). "The patients whose tumors presented a high expression of IGFBP2 had shorter OS (13 months) compared to those whose tumor presented none or a low expression of IGFBP2 (20 months)." (PMID 34830745, 2021). "Compared with short-term rhGH, long-acting PEG-rhGH did not significantly increase tumor-associated IGF-2 and IGFBP-2 expressions." (PMID 34899612, 2021). "It was reported that the IGFBP-2 was secreted by mature adipocytes around metastatic breast tumors compared with that in non-metastatic tumor tissue, resulting in the promotion of metastatic ability of MCF-7 cells." (PMID 32787888, 2020). "Our data indicate that IGFBP2 protects against ABS-induced double strand breaks and may thus favor tumor cell survival under reflux conditions." (PMID 30626422, 2019). "Unlike IGFBP3, IGFBP2 has been shown to promote tumorigenesis, metastasis, cancer stem cell expansion, and tumor angiogenesis." (PMID 29500455, 2018). "In ID8hPON2 cells, the expression profile of many genes known to regulate tumor growth including BRCA1, cyclin and cyclin-dependent kinase 20, PTK2, Hypoxia-upregulated protein 1, p21-activated kinase 3, IL-18, IL-33, IGF-1, IGFBP2 and RNA-binding protein 9, were identified." (PMID 29531225, 2018). "Thus, the association between an elevated serum (free) IGFBP‐2 concentration and a poorer prognosis is likely to reflect an increased tumor synthesis of IGFBP‐2, a suppressed PTEN level, and consequently an unopposed tumor growth." (PMID 29722920, 2018). "One molecular reason for this may be the expression levels of IGFBP in PaSCs: Tumor PaSCs have lower expression levels of IGFBP-3 and higher expression levels of IGFBP-2 compared to the normal PaSCs." (PMID 29475434, 2018). "These genes likely function as downstream effectors of STAT3 in GBM to regulate not only cell proliferation (e.g., GAS7, IGFBP2, MEOX2 and MXI1), and but also tumor-stroma interactions by modulating protein secretion (e.g., ANXA1, ARL4C, EMILIN1, EMP2, EXTL3 and PDIA4)." (PMID 29774125, 2018). "However, some changes were observed in the levels of expression of binding protein genes, with a decrease in IGFBP2, IGFBP3, and IGFBP4 expression and an increase in IGFBP7 expression with tumor progression." (PMID 28882129, 2017).
tumor (continued). "Selected examples include dendritic cell vaccines, patient-specific autologous tumor cell vaccines, and vaccines targeting various antigens enriched in tumor cells, such as folate receptor alpha, HER2, brachyury, insulin-like growth factor binding protein-2, survivin, and carcinoembryonic antigen." (PMID 28904804, 2017). "In the low-grade tumor area, ISH and IHC detected only slight levels of HOTAIR and IGFBP2." (PMID 28931862, 2017). "Correlation analysis indicated that the primary tumor transcript levels for IGFBP2 did not correlate with circulating IGFBP2 concentrations in the matched samples." (PMID 28732082, 2017). "Compared with the negative control group, the average tumor volume of tumors increased at slower rate in the sh-IGFBP2 group." (PMID 28977895, 2017). "Insulin-like growth factor binding protein 2 (IGFBP2), an important member of the IGFBP family of proteins, binds insulin, IGF1 and IGF2 in circulation, thereby modulating cell survival, differentiation, migration, and invasion in neoplasms." (PMID 28410230, 2017). "IGFBP-2 is up-regulated in an in vitro model of Her-2+ BC and recently multiple antigenic peptides (MAPs) comprising IGFBP-2 epitopes have been used to block tumour progression in a transgenic mouse model." (PMID 27050076, 2016). "Thus, the communication between adipocytes and tumor cells increased IGFBP-2 secretion, activated MMP-2 in tumor cells and promoted the durable expression of MMP-2." (PMID 25747684, 2015). "The in vitro and in vivo studies indicate that the mutant IGFBP-2 (lacking a large portion of the central linker domain) is able to inhibit tumour growth possibly by inhibition of angiogenesis." (PMID 25866791, 2015). "Insulin-like growth factor binding protein 2 (IGFBP-2) is of particular interest as in vitro studies have shown that it has a proliferative effect in mammary and other tumor cell lines and clinical studies have shown it to be a prognostic biomarker for many cancers." (PMID 26106415, 2015). "Given that levels of IGFBP-2 in ascites and serum were positively correlated, our findings support the concept that the elevated serum levels are attributable to an increased production of IGFBP-2 by the tumor." (PMID 26336825, 2015). "The results revealed that patients with IGFBP2 staining at or above the median had a significant reduction in both survival and recurrence-free survival time, independent of tumor stage." (PMID 26097693, 2015). "IGFBP2 is a member of the IGFBP family of proteins that has been reported to modulate both IGF and integrin signaling and is a mediator of cell growth, invasion and resistance in other tumor types." (PMID 26317790, 2015). "We found that, after postoperative radiotherapy plus chemotherapy, plasma IGFBP-2 levels did not vary significantly with sex, preoperative tumor size and MGMT promoter methylation status." (PMID 24690948, 2014). "IGFBP2 staining, on the other hand, exhibited no differential expression across the different tumor subtypes, with the exception of significantly lower expression in triple negative tumors as compared to all the other groups (p<0.001)." (PMID 24637962, 2014). "First, the use of the C-terminal antibody that identifies the full-length IGFBP2 protein and a shorter fragment showed that not all tumor samples presented the full-length protein." (PMID 24962328, 2014). "We selected 12 IGFBP2 positive and 7 IGFBP2 negative tumor RNAs for microarray expression analysis using Agilent whole human genome 4x44K arrays." (PMID 23767917, 2013). "In previous studies, TaqMan quantitative PCR was utilized to confirm the expression of several genes (decorin, IGFBP2, Thrsp, Sncg, SerpinG1) in MIN-O and tumor pairs and showed that this data correlated with the direction and fold change of the microarray data." (PMID 17147824, 2006).
tumor (continued). "Based on the correlation between IGFBP-2 serum levels and the corresponding gene expression as well as the normalization of IGFBP-2 levels during chemotherapy, we concluded that the increased serum level mainly originated from the tumour clone itself." (PMID 9716037, 1998). "Therefore, we hypothesized that IGFBP2 increases the expression of IDO by activating STAT3 signaling in PDAC, thereby inducing Treg differentiation and promoting tumor progression." (PMID 36556226, 2022). "Bioinformatic analysis and mechanistic assessment reveals IGFBP2 upregulated indoleamine 2, 3-dioxygenase (IDO) by activating signal transducer and activator of transcription 3 (STAT3) signaling in PDAC cells, thus inducing Treg differentiation and an immunosuppressive tumor microenvironment." (PMID 36556226, 2022). "Notably, deregulation of MACC1 or IGFBP2 did not affect tumor-cell-induced thrombin formation, which is considered of overriding importance for tumor-related thrombosis and metastasis." (PMID 34830078, 2021). "In terms of hematogenous metastasis, another oncogene, namely insulin-like growth factor binding protein-2 (IGFBP2), comes into consideration, which has surprisingly neither been associated with the oncogene MACC1, nor with tumor-cell-induced platelet activation." (PMID 34830078, 2021). "However, high expression of oncogenic factors including IGFBP2, PGF, and TGFB2 was found specifically in subset 4, suggesting a different functional role of fibroblasts in liver metastasis compared to the primary tumor." (PMID 34671197, 2021). "However, others report that aggressive cancers have little or no expression of IGFBP-2 compared with more differentiated forms of the tumours." (PMID 31903164, 2019). "Tumor samples from high-risk group A showed a higher mean overall IHC score for Anti-MSX1, Anti-CD271, Anti-ERRFI1, Anti-PTPRF, Anti-TNFRSF21, Anti-TNFRSF12a, and Anti-IGFBP2, but without significance." (PMID 30641895, 2019). "Similarly, the IGFBP-2 expression in tumor tissue varied without a clear trend (38.2% [95% CI 26.7–49.7%], 33.5% [95% CI 23.0–44.0%], and 36.0%; [95% CI 25.7–46.6%])." (PMID 30497427, 2018). "Thus, targeting IGFBP2 may serve as a potential therapeutic strategy for women with LAM and other female gender specific neoplasms." (PMID 28410230, 2017). "Thus, targeting IGFBP2 may serve as a potential therapeutic strategy for women with LAM and other gender specific neoplasms." (PMID 28410230, 2017). "In the progressed stage of tumor development IGFBP-2 seems not to be able to promote any longer growth inhibiting activities but enhanced expression might represent an effort to antagonize the effects of growth factors." (PMID 17118177, 2006). "IGFBP-2 and -3 were highly expressed but not differentially expressed across the tumour types." (PMID 15471544, 2004). "Furthermore, IGFBP-2 SDS were positively related to tumour size (P= 0.01) and fell significantly in patients following curative resection (P= 0.04), suggesting that circulating levels reflect tumour load." (PMID 11044360, 2000). "This suggests IGFBP-2 might not be a reliable tumor marker in septic patients." (PMID 38137505, 2023). "Moreover, DK1 also enhanced the expression of several other tumor suppressor genes that are related to this pathway such as FOXO, TP73, CDKN1A, Caspase, CYCS, and GADD45A while impeded the expression of other proto-oncogenes namely PIK3R3, BCL-2, IGFBP2, HGF, and FGF." (PMID 34204873, 2021). "Immunohistochemical analysis showed that the IGFBP2 expression was not detectable in the primary tumor of a patient with low blood IGFBP2 level but was markedly elevated in the tumor of a patient with high blood IGFBP2, suggesting that blood IGFBP2 levels may reflect IGFBP2 expression in the tumors." (PMID 24069370, 2013).
tumor (continued). "However, the observation that transgenic mice overexpressing IGFs or IGFBP-2 do not develop adrenal tumors indicates that IGF-II alone is not a tumor initiator for adrenal cells but rather a tumor progression factor that requires additional effectors for triggering adrenal tumorigenesis." (PMID 22927847, 2012). "MSCs that do not migrate well to tumor CM (MSC‐8, ‐21, and ‐22) exhibited a slight increase in levels of IGFBP2 in comparison with those with efficient migration potential (MSC‐1, ‐13, and ‐19)." (PMID 29321953, 2018).